CYP1A1 (cytochrome P450 family 1 subfamily A member 1)
Diseases named in the same sentence as CYP1A1 in open-access papers (continued):
Sharing a sentence is not in itself a finding about the gene and the disease.
melanoma (9 papers, 2012 to 2026). A malignant, usually aggressive tumor composed of atypical, neoplastic melanocytes. "Western blotting revealed an elevated level of CYP1A1 protein in resistant melanoma cell lines, but this was statistically significant only for WM9 R cell line." (PMID 39175042, 2024). "Recent studies indicate a heightened expression of CYP1A1 in G0-positive melanoma cells, emphasizing its significance in cancer progression." (PMID 37844995, 2023). "More recently it was found that benzo[a]pyrene that is known to activate AHR and induce CYP1A1 represses melanogenesis in B16F10 mouse melanoma cells." (PMID 29632489, 2018). "Studies indicate that KLF5 can enhance the expression of CYP1A1, which are involved in inducing the expression of proinflammatory cytokines (such as TNF) that can influence melanoma progression." (PMID 39835132, 2024). "Ability of melanoma cells to metabolize dacarbazine was determined by expressional analysis of CYP1A1, CYP1A2, CYP2E1 followed by CYP1A1 protein level evaluation by the ELISA method." (PMID 36533319, 2023). "The present study determined the mRNA levels of the cytochromes CYP1A1, CYP1A2 and CYP2E1, as well as the protein levels of cytochrome CYP1A1 in melanoma cells." (PMID 36533319, 2023). "In this study, we found six mitochondria-related genes, BTG2, CP, LRIG1, CYP1A1, GBP2, and MBNL1, which might be targets of quercetin in melanoma and play crucial roles in melanoma." (PMID 37869567, 2023). "Treatment with 1 nM TCDD for 24 hours also significantly increased CYP1A1 expression in A375 melanoma cells (data not shown)." (PMID 22815870, 2012). "Combining the results of RNA-seq, molecular docking, and bioinformatics analysis, we found six mitochondria-related genes, BTG2, CP, LRIG1, CYP1A1, GBP2, and MBNL1, which might be targets of quercetin in melanoma and provide an available targeting therapy strategy for melanoma." (PMID 37869567, 2023).
glioma (7 papers, 2010 to 2024). A benign or malignant brain and spinal cord tumor that arises from glial cells (astrocytes, oligodendrocytes, ependymal cells). "The CYP1A1 gene is located in the 15q22-24 region, and people with a hereditary predisposition towards glioma have exhibited associations between the disease and low-penetrance markers in the 15q23-q26.3 region which overlaps this locus." (PMID 22649665, 2010). "Isogenic cell line pairs CHO/CHO1A137, SW480/SW480-2W126 and the glioma cell line U8738 were used as controls for the expression of CYP1A1, 2W1 and 1B1, respectively." (PMID 34556703, 2021). "We found that IL4I1 was highly expressed in glioma cell lines (LN018, LN215, LN229, and LN319), CYP1A1 was low expressed in glioma cell lines (LN215, LN229, LN319, and BS149), OGDHL was low expressed in LN018, and ASMT was lowly expressed in glioma cell lines (LN018, LN215, LN229, LN319, and BS149)." (PMID 36407768, 2022). "Then, four genes (IL4I1, CYP1A1, OGDHL, and ASMT) were screened out by univariate and multivariate cox regression analysis of tryptophan metabolism genes, and a risk score model for predicting the overall survival (OS) of glioma patients was constructed." (PMID 36407768, 2022). "The mechanism of this interaction was not well known, and maybe this combined or crossover effect on some glioma- related risk factors could lead to the interaction between PPAR G and CYP1A1 gene on CAD risk." (PMID 28380465, 2017). "Interestingly, CASP3 and CYP1A1 were previously identified to be related to glioma and used to predict the survival for glioma patients, the high expression of CDK1 is associated with the malignant progression in glioma, and mutations in MT-CO1 contribute to brain tumours." (PMID 38642129, 2024). "The construction of our predictive model was based on the expression levels of four genes (IL4I1, CYP1A1, OGDHL, and ASMT) in glioma tissues." (PMID 36407768, 2022). "At the same time, we verified the expression of IL4I1, CYP1A1, OGDHL, and ASMT four genes in glioma specimens and cell lines in GES4260 and GES15824." (PMID 36407768, 2022). "Combined with the results of our univariate Cox analysis, we can conclude that IL4I1 plays a tumor-promoting role and CYP1A1, OGDHL, and ASMT all play protective roles in gliomas." (PMID 36407768, 2022). "Among them, the expression of IL4I1 in glioma patients was greater than of normal samples, while the CYP1A1, OGDHL, and ASMT were lower in glioma samples." (PMID 36407768, 2022). "Since studies with hepatic tissue from BNF-treated mice and C6 glioma cell point to the catalytic activity of CYP1A1 and 1A2 as possible sources of ROS, we used COS cells stably expressing CYP1A1 to further ascertain this possibility." (PMID 29098061, 2017).
laryngeal carcinoma (7 papers, 2012 to 2022). Carcinoma that arises from the laryngeal epithelium. "Many studies have investigated the association between CYP1A1 rs1048943 and rs4646903 polymorphisms and laryngeal cancer risk, but their results have been inconsistent." (PMID 26578427, 2016). "The similar results were found between CYP1A1 rs4646903 and laryngeal cancer risk for G allele carriers versus AA." (PMID 26578427, 2016). "Significant association of CYP1A1 rs1048943 and rs4646903 polymorphisms and laryngeal cancer risk was demonstrated." (PMID 26578427, 2016). "In conclusion, this meta‐analysis suggests that the CYP1A1 rs1048943 and rs4646903 polymorphisms are associated with laryngeal cancer risk among Asian populations." (PMID 26578427, 2016). "Several studies have investigated associations between CYP1A1 rs1048943 and rs4646903 polymorphisms and laryngeal cancer risk, but there is the perception that the findings have been inconsistent." (PMID 26578427, 2016). "Meta‐analyses of total studies showed that CYP1A1 rs1048943 and rs4646903 polymorphisms were associated with laryngeal cancer risk for the homozygote G/G and G allele carriers (A/G + G/G) when compared with the homozygous wild‐type genotype (A/A)." (PMID 26578427, 2016). "In this meta‐analysis, we assessed 10 published studies involving comprising 748 laryngeal cancer cases and 1558 controls of the association between CYP1A1 rs1048943 and rs4646903 polymorphisms and laryngeal cancer risk." (PMID 26578427, 2016). "The present meta‐analysis investigating the relationship between CYP1A1 rs1048943 and rs4646903 polymorphisms and laryngeal cancer risk provided the most comprehensive evidence." (PMID 26578427, 2016). "Many researches focused on the association of CYP1A1 polymorphism with susceptibility to laryngeal cancer." (PMID 24151610, 2013). "The association between CYP1A1 rs4646903 and laryngeal cancer risk was performed by meta‐analysis." (PMID 26578427, 2016). "The association between CYP1A1 rs1048943 and laryngeal cancer risk was performed by meta‐analysis." (PMID 26578427, 2016). "Hence, we performed a meta‐analysis of all eligible studies to derive a more precise estimation of the associations of CYP1A1 rs1048943 and rs4646903 polymorphisms with laryngeal cancer." (PMID 26578427, 2016). "Evaluation of publication bias for G allele carriers versus AA between CYP1A1 rs1048943 and laryngeal cancer risk showed that the Egger test was not significant (P = 0.615)." (PMID 26578427, 2016). "CYP1A1 MspI polymorphism was found to be a risk factor for laryngeal cancer in Caucasians (OR = 1.29) but not in Asians (OR = 1.38)." (PMID 24151610, 2013).
male infertility (7 papers, 2013 to 2025). The inability of the male to effect fertilization of an ovum after a specified period of unprotected intercourse. "In the article, “Association between CYP1A1 rs4646903 T > C genetic variations and male infertility risk: A meta-analysis”, which appears in Volume 98, Issue 31 of Medicine Dr. DongLiang Lu's degree should appear as MD and affiliation a." (PMID 31464968, 2019). "Based on an Indian study,the pathogenesis of male infertility was associatedwith the CC genotype of the CYP1A1*2Apolymorphism." (PMID 28868835, 2017). "Epidemiological studies have evaluated the association between 3801T>C polymorphism of CYP1A1 gene and the risk for idiopathic male infertility, but the results are inconclusive." (PMID 24466186, 2014). "The current meta-analysis provides evidence of a significant association between CYP1A1 3801T>C polymorphism and idiopathic male infertility risk." (PMID 24466186, 2014). "Pooled odds ratios with 95% confidence intervals were used to assess the strength of the association between CYP1A1 3801T>C polymorphism and idiopathic male infertility risk." (PMID 24466186, 2014). "So there are contradictory reports on the role of CYP1A1 polymorphism on male infertility." (PMID 27220890, 2016). "Psychological factor and CYP1A1 single nucleotide polymorphisms (SNPs) might separately act as a risk factor for male infertility." (PMID 27220890, 2016). "Results of meta-analysis for 3801T>C polymorphism of CYP1A1 and idiopathic male infertility risk." (PMID 24466186, 2014). "So, it is concluded that CYP1A1 gene polymorphisms and psychological distress act independently in developing abnormal sperm characteristics and thereby might contribute to pathogenesis of male infertility." (PMID 27220890, 2016). "In addition, association of CYP1A1 and estrogen polymorphisms with impaired spermatogenesis implies that both genetic and environmental factors contribute to testicular dysfunction, which can lead to sperm damage, deformity, and eventually male infertility." (PMID 24466186, 2014). "This may be the underlying mechanism by which the CYP1A1 3801C allele resulted in male infertility." (PMID 24466186, 2014). "Thus, we are not sure whether there is a significant association between the CYP1A1 3801T>C polymorphism and increased male infertility risk in the whole population." (PMID 24466186, 2014). "Thus, we hypothesize that 4-t-OP exposure combined with polymorphisms in CYP2C9, CYP2C19 and/or CYP1A1 may interact to impart increased risk of male infertility." (PMID 23555028, 2013). "Lu and colleagues reported that CYP1A1 polymorphisms were not involved in the etiology of male infertility." (PMID 29766145, 2018). "It is concluded that CYP1A1 gene polymorphisms and psychological distress act independently but do not interact with each other in pathogenesis of male infertility." (PMID 27220890, 2016). "However, other papers showed that CYP1A1*2A CC and the combination of GSTM1 and CYP1A1*2C genotypes were associated with increased risk of male infertility, while CYP1A1*2A TC genotype showed a non-significant increased risk of male infertility." (PMID 29766145, 2018).
pneumonia (7 papers, 2019 to 2026). An acute, acute and chronic, or chronic inflammation focally or diffusely affecting the lung parenchyma, caused by an infection in one or both of the lungs (by bacteria, viruses, fungi, or mycoplasma.). "CYP1A1 has been extensively studied in pneumonia, and an association between CYP1A1 polymorphisms and the risk of pneumonia has been reported." (PMID 38978778, 2024). "CYP1A1 gene was associated with pneumonia and ARDS in our previous investigations, so we included in our analysis three sites of CYP1A1 gene (rs2606345, rs4646903 and rs1048943) studied on a smaller sample." (PMID 30890150, 2019). "The abnormal expression of CYP1A1 and MUC5AC contributes to the progression of pneumonia." (PMID 38137330, 2023). "The study found that QKL treatment led to an increase in the mRNA expression of Cyp1a1, which suggests that this may be one of the mechanisms by which QKL helps to prevent pneumonia." (PMID 37362920, 2023).
Sepsis (7 papers, 2018 to 2023). Sepsis is defined as life-threatening organ dysfunction caused by a dysregulated host response to infection. "Additional work on genome-wide association is required to understand how CYP1A1 deficiency modulates the gut microbiota against MRSA-induced sepsis." (PMID 35572636, 2022). "However, the detailed effect of CYP1A1 on intestinal barrier function in sepsis caused by drug-resistant bacteria remains to be explored." (PMID 35572636, 2022). "To further ascertain the role of Cyp1a1 in the development of MRSA-induced sepsis, we used Cyp1a1–/– and wild-type littermates (Cyp1a1+/+ mice)." (PMID 35572636, 2022). "Our previous study demonstrated that CYP1A1 mRNA expression levels are elevated in PBMCs of patients with sepsis, and strongly correlate with sequential organ failure assessment (SOFA) scores." (PMID 35572636, 2022). "Since the data pointed to the abundance of E. faecalis in Cyp1a1+/+ mice, which succumbed to sepsis, we investigated the direct influence of E. faecalis treatment on gut barrier integrity." (PMID 35572636, 2022). "The research covered in this report showed that genetic ablation of CYP1A1 contributes to intestinal barrier protection against MRSA-induced sepsis by shifting the microbiota composition to decrease cadaverine metabolite levels in a non-AHR-dependent manner." (PMID 35572636, 2022). "Intriguingly, we previously reported the possible AHR-independent regulation of CYP1A1 expression and CYP1A1-induced proinflammatory responses during the progression of inflammation and sepsis." (PMID 35572636, 2022). "Cyp1a1+/+ littermates succumbed to sepsis, whereas Cyp1a1–/– mice showed markedly reduced mortality after MRSA challenge (hazard ratio = 4.739; 95% CI: 1.23–18.25; P = 0.003)." (PMID 35572636, 2022). "As an important source of 12(S)-HETE, our data showed that platelet counts are abundantly increased in the peritoneal cavity following LPS, E.coli, or sepsis impact, while CYP1A1 overexpression in PMs was incapable to recruit platelets in PLFs." (PMID 32366266, 2020). "Taken together, these results indicate that CYP1A1 in macrophages plays a critical role in host defence against invading bacteria during sepsis." (PMID 32366266, 2020). "Collectively, our results identify a novel therapy target, CYP1A1, regulating macrophage inflammatory responses and phagocytosis during sepsis." (PMID 32366266, 2020). "Therefore, a mouse model of selective CYP1A1 deletion in IECs will be needed to fully demonstrate the role of the CYP1A1-microbiota metabolic axis in sepsis-induced epithelial barrier dysfunction." (PMID 35572636, 2022). "CYP1A1 plays a critical role in regulating the inflammatory response and phagocytosis in individuals with sepsis and may modulate the gut microbiota." (PMID 35572636, 2022). "Mice injected with CYP1A1-overexpressing PMs were more susceptible to CLP- or E. coli-induced mortality and bacteria invading, while Rhapontigenin, a selective CYP1A1 inhibitor, improved survival and bacteria clearance of mice in sepsis." (PMID 32366266, 2020). "However, the effect of CYP1A1 on pathology and mortality in mice challenged with polymicrobial sepsis, trauma, or LPS requires further investigation." (PMID 32935470, 2020). "Based on these findings, analogues of 12(S)-HETE or selective antagonists of CYP1A1, especially Rhapontigenin, may be the promising treatments against inflammatory diseases and sepsis." (PMID 32366266, 2020). "Macrophage CYP1A1 disruption could be a promising strategy for treating sepsis." (PMID 32366266, 2020). "In this study, we identified CYP1A1 as a critical regulator of inflammatory responses and phagocytosis in sepsis and described two novel CYP1A1-invovled signalling pathways, CYP1A1–12(S)HETE−JNK − AP-1 and CYP1A1-SR-A, that may be promising targets for treating sepsis or other inflammatory diseases." (PMID 32366266, 2020).
Sepsis (continued). "Taken together, these results further support that the ABX-driven gut microbiome perturbation to Cyp1a1–/– mice negates the survival benefit and disrupts intestinal barrier integrity after MRSA-induced sepsis." (PMID 35572636, 2022). "Altogether, these findings confirmed the regulatory effects of CYP1A1/12(S)-HETE/JNK/AP-1 axis in vivo, while Rhapontigenin reduces the mortality and pro-inflammatory biomarkers from sepsis." (PMID 32366266, 2020). "The transcriptional expression of (A) Cyp1a1, (B) Cyp2a5, (C) Cyp3a11 was significantly downregulated in SMPD1+/+ mice at 24 h following sepsis induction." (PMID 30326559, 2018). "The potential ability to suppress CYP1A1 or inhibit intestinal cadaverine-HRH4 signaling to enhance IEC junctions, or a combination of these two strategies, warrants further study to develop more effective sepsis treatment." (PMID 35572636, 2022). "Furthermore, treatment of mice with JNK and AP-1 inhibitors prior to Ad-NC and Ad-CYP1A1 PMs adoptive transfer decreased mice mortality and pro-inflammatory biomarkers in the E. coli- or CLP-induced sepsis model." (PMID 32366266, 2020). "Taken together, these results describe a novel CYP1A1‐related signaling pathway, CYP1A1‐NF‐κB‐iNOS, which may be a promising target for ALI treatment, especially during sepsis." (PMID 32935470, 2020). "Furthermore, LSCM confirmed that CYP1A1 protein expression and JNK/AP-1 phosphorylation were enhanced in peripheral monocytes of sepsis patients." (PMID 32366266, 2020). "To correlate the specific bacterial taxa with cadaverine levels following MRSA-induced sepsis, we performed 16S ribosomal DNA sequencing and clarified the caecal microbial diversity and composition of Cyp1a1+/+ and Cyp1a1–/– mice in the presence or absence of MRSA challenge at 24 h." (PMID 35572636, 2022). "Notably, we described for the first time the gut microbiota in Cyp1a1 KO mice under both basal conditions and MRSA-induced sepsis conditions, confirming the previously held notion that inhibiting CYP1A1 contributes to maintaining homeostasis by changing microbiota-associated cascade signaling." (PMID 35572636, 2022). "Although the present study suggests that host CYP1A1 plays a direct or indirect role in microbiota-mediated cadaverine metabolism during MRSA-induced sepsis, other mechanisms may exist, with or without the involvement of the microbiome." (PMID 35572636, 2022). "The expression rate of Cyp1a1 in SMPD1+/+ animals significantly decreased from a median control level set to 0.0 (IQR 25%: −0.08 and IQR 75%: 0.07) log2 fold change to −1.04 (IQR 25%: −1.83 and IQR 75%: −0.93) log2 fold change at 24 h following polymicrobial sepsis induction." (PMID 30326559, 2018). "However, no studies so far have investigated the relationships among CYP1A1, 12(S)-HETE and JNK/AP-1 in macrophages during inflammation or sepsis." (PMID 32366266, 2020).
head and neck cancer (6 papers, 2008 to 2023). A primary or metastatic malignant neoplasm affecting the head and neck. "The MspI SNP in the CYP1A1 gene indicated a 34% increased risk of head and neck cancer in carriers of the TC and CC genotype compared to carriers of carriers of TT carriers." (PMID 37391706, 2023). "Some reportsalso suggested the association of CYP1A1*2Cpolymorphism with increased risk of solid tumorssuch as head and neck cancer in patients with Indiandescent." (PMID 26464823, 2015). "In any case, neither the previous meta- and pooled analysis onCYP1A1 and risk of head and neck cancer nor the recently published metaand pooled analysis on oral and pharyngeal cancer founda significant association between CYP1A1(Ile/Val) polymorphism and oral and pharyngeal cancer." (PMID 19259333, 2008). "Simultaneously, the expression of the cytochrome P450 subtypes 1A1 and 1B1 (CYP1A1 and CYP1B1) genes increased in the head and neck cancer (HNC) cell line, elucidating the involvement of cytochrome P450 in OSCC." (PMID 35096060, 2022).